ALPL (alkaline phosphatase, biomineralization associated)
Diseases named in the same sentence as ALPL in open-access papers (continued):
Sharing a sentence is not in itself a finding about the gene and the disease.
glioblastoma (3 papers, 2021 to 2025). The most malignant astrocytic tumor (WHO grade IV). "Low expression of ALPL has also been associated with the pathogenesis of glioblastoma multiform." (PMID 34141614, 2021).
Insulin resistance (3 papers, 2020 to 2021). Increased resistance towards insulin, that is, diminished effectiveness of insulin in reducing blood glucose levels. "Additionally, knocking down the ALPL gene decreased the expression of leptin, which plays a key role in adipocyte systemic signaling and insulin resistance." (PMID 34198561, 2021).
melanoma (3 papers, 2018 to 2020). A malignant, usually aggressive tumor composed of atypical, neoplastic melanocytes. "The objective of this study was to quantify the processing times, cell yields and viabilities of MACS and FACS separations using defined mixtures of osteogenically primed SVF cells and A375 human melanoma cells based on their expression of ALPL." (PMID 30659223, 2019). "To do this we created a series of defined mixtures of osteogenically primed SVF (ALPL+) and A375 human melanoma (ALPL−) cells and separated them using FACS and MACS." (PMID 30659223, 2019).
myocardial infarction (3 papers, 2020 to 2024). Gross necrosis of the myocardium, as a result of interruption of the blood supply to the area, as in coronary thrombosis. "Whether exosomal mRNA ALPL increases during the progression of coronary plaque to acute myocardial infarction requires further study." (PMID 34490374, 2021).
ovarian carcinoma (3 papers, 2017 to 2022). A malignant neoplasm originating from the surface ovarian epithelium. "The strongest association with ovarian cancer risk in BRCA1 carriers was observed for rs12025623 located at 1p36.12 (p = 7 × 10−3) in an intron of the ALPL gene." (PMID 27796716, 2017). "Another study suggested that overexpression of ALPL can inhibit the migration and invasion of HGSOC ovarian cancer cells." (PMID 33858415, 2021).
serous ovarian cancer (3 papers, 2021 to 2024). "Some studies have observed a relationship between low ALPL expression and chemo-resistance of high-grade serous ovarian cancer (HGSOC) cells to paclitaxel." (PMID 38915066, 2024). "Moreover, overexpression of ALPL was observed to curtail migration and invasion in high-grade serous ovarian cancer (HGSOC) cell models." (PMID 38915066, 2024). "However, another study proposed that ALPL could inhibit the motility and aggression of serous ovarian cancer cells." (PMID 34222474, 2021). "Low expression of ALPL was found to be inversely related to the FIGO stages and histological grades in a cohort of 90 patients with serous ovarian cancer (SOC)." (PMID 38915066, 2024).
asthma (2 papers, 2018 to 2020). "A six-gene signature (CLC, CPA3, DNASE1L3, IL1B, ALPL, and CXCR2) can differentiate asthma patients from controls, discriminate inflammatory phenotypes of asthma and predict the ICS response, but this method is not currently available." (PMID 30598830, 2018). "Both the six gene signature (6GS: CPA3, DNASE1L3, CLC, IL1B, ALPL, and CXCR2) and T‐helper 2 signature (TH2S: CLCA1, SERPINB2, and POSTN) are proposed as biomarkers in the identification of inflammatory phenotypes of asthma in induced sputum and epithelial brushings, respectively." (PMID 31903716, 2020).
breast carcinoma (2 papers, 2018 to 2024). "Moreover, qPCR assays demonstrated that exosomes from hnRNPA2B1 KD breast cancer cells inhibited the expression of the osteoblast differentiation marker genes ALPL, OCN and OSX, an effect that was reversed by exosomes from hnRNPA2B1 KD breast cancer cells transfected with miR-6881-3p mimics." (PMID 38448424, 2024).
Calcium nephrolithiasis (2 papers, 2019 to 2022). The presence of calcium-containing calculi (stones) in the kidneys. "Moreover, four SNPs at four loci, rs6667242 at ALPL (p = 0.02999, OR = 0.8331), rs1544935 at KCNK5 (p = 0.01341, OR = 0.7804), rs7328064 at DGKH (p = 0.007452, OR = 1.211) and rs13041834 at BCAS1 (p = 0.03897, OR = 0.8409), were suggestively associated with calcium nephrolithiasis." (PMID 35741705, 2022). "Moreover, four SNPs at four loci, rs6667242 at ALPL (p = 0.02999, OR = 0.8331), rs1544935 at KCNK5 (p = 0.01341, OR = 0.7804), rs7328064 at DGKH (p = 0.007452, OR = 1.211) and rs13041834 at BCAS1 (p = 0.03897, OR = 0.8409), were suggestively associated with the risk of calcium nephrolithiasis." (PMID 35741705, 2022).
colon carcinoma (2 papers, 2018 to 2022). "In our study, ALPL was a high-risk gene that was lowly expressed in colon cancer tissues." (PMID 35991564, 2022). "However, the opposite was true for the role of ALPL in colon cancer." (PMID 35991564, 2022). "ALPL, APOL6, SON, VWF, FITM2, and ZEB1-AS1 were significantly differentially expressed in normal and colon cancer tissues." (PMID 35991564, 2022).
Encephalopathy (2 papers, 2020 to 2021). Encephalopathy is a term that means brain disease, damage, or malfunction. "A case report describes that TNAP deficiency, due to two compound heterozygous null mutations in the ALPL gene, can result in severe and progressive encephalopathy with a fatal onset of the disease." (PMID 33477631, 2021).
Hypertension (2 papers, 2014 to 2018). The presence of chronic increased pressure in the systemic arterial system. "The patients with hypertension exhibited unchanged levels of ALPL, a tissue-type alkaline phosphatase gene expressed by many non-vascular cells (including osteoblasts) but also by vascular lineage CSPCs." (PMID 24759906, 2014).
leukemia (2 papers, 2021 to 2022). A malignant (clonal) hematologic disorder, involving hematopoietic stem cells and characterized by the presence of primitive or atypical myeloid or lymphoid cells in the bone marrow and the blood. "Moreover, a role of ALPL was described in malignant leukemia, in which changes in its levels can be used to identify rare populations of highly refractory malignant cells." (PMID 35884475, 2022).
lung carcinoma (2 papers, 2018 to 2021). "The effect of ALPL on the metastatic capacity of LUAD cells was verified in vivo in a nude mouse xenograft model of lung cancer metastasis." (PMID 33858415, 2021). "ALPL overexpression significantly reduced the number and size of A549 lung cancer metastases." (PMID 33858415, 2021).
metabolic syndrome (2 papers, 2021 to 2024). A cluster of metabolic risk factors for CARDIOVASCULAR DISEASES and TYPE 2 DIABETES MELLITUS. "Thus, the inhibition of RMT to non-RMT shifts using ALPL inhibitors might be an effective way to prevent cognitive decline caused by HFD-induced metabolic syndrome." (PMID 38685040, 2024).
periodontitis (2 papers, 2023). An acute or chronic inflammatory process that affects the tissues that surround and support the teeth. "Similar alterations were observed in the longitudinal experimental periodontitis model across all age groups with elevated MMP1, MMP3, MMP9, and ALPL." (PMID 38098978, 2023).
Acidosis (1 paper, 2024). Abnormal acid accumulation or depletion of base. "ENPP1 as well as ALPL activity are increased during acidosis whereby lactic acidosis exerts the strongest effect." (PMID 38195466, 2024).
appendicitis (1 paper, 2023). Acute inflammation of the vermiform appendix. "Using the combined criteria of either ALPL/IL8RB > 20% or DEFA1 > 10%, all 100% of cases of appendicitis were detected." (PMID 36759691, 2023). "The ALPL and IL8RB markers were principally elevated in cases of abdominal infections such as appendicitis, that are thought to be biofilm infections." (PMID 36759691, 2023). "For example, using the ALPL + IL8RB pre-set threshold of 20%, we detected nine out of 10 cases of appendicitis." (PMID 36759691, 2023).
Azoospermia (1 paper, 2024). Absence of any measurable level of sperm,whereby spermatozoa cannot be observed even after centrifugation of the semen pellet. "Measurement of the enzymatic activity of ALPL in the canine seminal plasma has been used for the diagnosis of incomplete ejaculation or azoospermia in dogs, and a reduced concentration of ALPL in the seminal plasma suggests bilateral obstruction of the vas deferens or epididymis." (PMID 38921038, 2024).
bone metastasis (1 paper, 2019). Transfer of a neoplasm from its primary site to bones. "However, recent studies by Rao and colleagues mechanistically supports a key functional role of ALPL and osteomimicry in invasion, epithelial plasticity, and bone metastasis in patients with bone metastatic prostate cancer." (PMID 31136607, 2019).
cutaneous melanoma (1 paper, 2021). A primary melanoma arising from atypical melanocytes in the skin. "The genetic variants of ALPL are significantly associated with cutaneous melanoma-specific survival in the folate metabolic pathway genes." (PMID 34141614, 2021).
enamel hypoplasia (1 paper, 2014). "In a mouse model, if HPP (including enamel hypoplasia) results from a deficiency of the tissue-nonspecific isoenzyme of alkaline phosphatase (ALPL) function, the enamel phenotype can be rescued with subcutaneously administered enzyme replacement therapy." (PMID 24828138, 2014).
Hyperglycemia (1 paper, 2021). An increased concentration of glucose in the blood. "Osteoblast markers, except for ALPL, were reduced, and a shift from osteogenesis towards adipogenesis was noticed in the presence of hyperglycemia-derived ROS in vitro." (PMID 33923498, 2021). "On the other hand, short-term incubation under hyperglycemia resulted in reduced ALPL, OC and collagen levels." (PMID 33923498, 2021). "Two independent clinical trials showed that osteoblastic ALPL secretion, OC levels and collagen synthesis are significantly lower in chronic hyperglycemia, and also after glucose-loading in healthy individuals." (PMID 33923498, 2021).
hypocalciuric hypercalcemia (1 paper, 2024). "Among patients with hypocalciuric hypercalcemia, two index cases (CA0121 and CA0128) had novel variants in the ALPL gene (one large duplication and one missense, respectively)." (PMID 38586466, 2024).
hypothyroidism (1 paper, 2021). Abnormally low levels of thyroid hormone. "Of notice, three patients of the ALPL- and two of the ALPL+ group previously had profound hypothyroidism, which may have contributed to impaired ALP activity." (PMID 34258332, 2021). "Furthermore, possible secondary reasons for hypophosphatasaemia including antiresorptive treatment and previously manifest hypothyroidism were more present in the ALPL- group (8/11), compared with the ALPL+ group (4/12)." (PMID 34258332, 2021).
liver diseases (1 paper, 2021). "We found on PheWAS that genetic variants in/near the genes coding for ALT (GPT), AST (GOT1/GOT2), and ALP (ALPL) did not themselves associate with liver diseases or other diagnoses suggesting that the liver enzymes are likely not themselves pathogenic." (PMID 33547301, 2021).
lung adenocarcinoma (1 paper, 2024). A carcinoma that arises from the lung and is characterized by the presence of malignant glandular epithelial cells. "Concurrently, another investigation posited that ALPL specifically mitigates lung adenocarcinoma (LUAD) cell metastasis by interacting with the p-ERK/c-Myc/RhoA signaling axis." (PMID 38915066, 2024).
lung squamous cell carcinoma (1 paper, 2021). "A human lung squamous cell carcinoma (LUSC) cell line (SK-MES-1) stably overexpressing ALPL was also generated." (PMID 33858415, 2021).
magnesium deficiency (1 paper, 2016). A nutritional condition produced by a deficiency of magnesium in the diet, characterized by anorexia, nausea, vomiting, lethargy, and weakness. "Magnesium deficiency is shown to impair vitamin B6 status by inhibiting plasma ALPase activity in rat, suggesting that the activity of tissue non-specific ALPase (ALPL) is repressed under hypomagnesaemia condition." (PMID 27458382, 2016).
microcephaly (1 paper, 2025). A congenital or acquired developmental disorder in which the circumference of the head is smaller than normal for the person's age and sex. "Similarly, genes such as PRKDC, ALPL, and KIF23, which are linked to microcephaly (scores ranging from 0.40 to 0.45), are involved in key cellular functions such as DNA repair, motor protein activity, and cytokinesis." (PMID 41033462, 2025).
Myalgia (1 paper, 2021). "Additionally, myalgia fits as a less specific symptom, i.e., we diagnosed adult HPP supported by the presence of a likely pathogenic ALPL variant." (PMID 33191482, 2021).
papillary thyroid carcinoma (1 paper, 2021). "We detected the expression of ALPL and CD11c in papillary thyroid carcinoma (PTC) and paracancerous tissue specimens (N=10)." (PMID 34141614, 2021).
periodontal disorder (1 paper, 2021). An inflammatory process of the gingival tissues and/or periodontal membrane of the teeth, resulting in an abnormally deep gingival sulcus, possibly producing periodontal pockets and loss of alveolar bone support. "Collectively, these results suggested ALPL+/− mice exhibited tooth defects similar to HPP-associated periodontal disorder." (PMID 33823913, 2021).
pneumonia (1 paper, 2022). An acute, acute and chronic, or chronic inflammation focally or diffusely affecting the lung parenchyma, caused by an infection in one or both of the lungs (by bacteria, viruses, fungi, or mycoplasma.). "A history of fractures, pneumonia, and impaired physical function in childhood were also more likely to be present in patients with ALPL mutation, albeit without statistical significance." (PMID 36514157, 2022). "Moreover, fractures, pneumonia, dental disease, and impaired function in childhood were more common in heterozygous mutation positive individuals than in patients with low ALP, but without mutation in the ALPL gene." (PMID 36514157, 2022).
prediabetes (1 paper, 2022). "The PBMC-isolated from 25 patients with prediabetes (25/28) expressed ALPL, BGLAP, COL1A1, and RUNX2/PPAR and the PBMC-isolated from 15 patients with normoglycemia (15/17) expressed those genes." (PMID 35237235, 2022).
prostate tumor (1 paper, 2025). "Specifically, upon exposure to the primary prostate tumor epithelial spheroids, we observed increased expression of ALPL, a gene marker for osteoblast differentiation." (PMID 40596459, 2025).
renal cell carcinoma (1 paper, 2021). "Forced expression of ALPL cDNA in renal cell carcinoma (RCC) cell lines resulted in decreased migratory property and cell viability compared with the controls." (PMID 34943845, 2021).
thyroid (1 paper, 2021). "In the UALCAN database, ALPL had higher expression in thyroid carcinoma tissue than normal thyroid tissue (p < 0.001)." (PMID 34141614, 2021).
thyroid cancer (1 paper, 2021). "Our study found the potential mechanism, that hsa-miR-204-5p regulates ALPL so that dendritic cells activated, which may play a critical role in thyroid carcinoma prognosis." (PMID 34141614, 2021). "The mechanism of hsa-miR-204-5p regulating ALPL and activated dendritic cells might play an important role in thyroid carcinoma." (PMID 34141614, 2021). "Our results suggested that ALPL is an important gene that could influence the prognosis of thyroid carcinoma." (PMID 34141614, 2021). "In summary, our study found a potential mechanism in which hsa-miR-204-5p regulated ALPL in activated dendritic cells, which may allow them to play a critical role in thyroid carcinoma." (PMID 34141614, 2021). "Besides, immunohistochemistry (IHC) assays were conducted to detect the expression of a dendritic cell marker (CD11c) and ALPL in thyroid carcinoma (TC) and paracancerous tissues." (PMID 34141614, 2021). "At the cellular level, in the CCLE database, ALPL and ITGAX were expressed in various thyroid carcinoma cell lines." (PMID 34141614, 2021). "At the cellular level, ALPL and ITGAX were expressed in various thyroid cancer cell lines." (PMID 34141614, 2021). "A dimensional validation was performed to explore the expressions of ALPL and CD11c (dendritic cell marker) in thyroid carcinoma, normal thyroid tissue, and cell lines." (PMID 34141614, 2021). "Finally, due to the longer OS of thyroid cancer, we could not use IHC to verify the effects of ALPL and CD11c on the prognosis of thyroid cancer." (PMID 34141614, 2021).
undifferentiated thyroid carcinoma (1 paper, 2021). "The expression of ALPL and CD11c should be verified with a larger sample size, especially follicular, medullary, and undifferentiated thyroid carcinoma." (PMID 34141614, 2021).
vitamin D deficiency (1 paper, 2018). A nutritional condition produced by a deficiency of VITAMIN D in the diet, insufficient production of vitamin D in the skin, inadequate absorption of vitamin D from the diet, or abnormal conversion of vitamin D to its bioactive metabolites. "At the final stage, the vitamin D deficiency becomes very severe and 1,25(OH)2D synthesis is markedly inhibited, the calcitriol concentration decreases, and subsequently absorption of both calcium and phosphorus is impaired, along with persistent elevation of PTH and increased ALPL." (PMID 29904370, 2018).